ALB (albumin)
Diseases named in the same sentence as ALB in open-access papers (continued):
Sharing a sentence is not in itself a finding about the gene and the disease.
bladder cancer (46 papers, 2012 to 2026). "Low serum albumin has been identified as an independent predictor of poor long-term prognosis in bladder cancer, with an increased risk of postoperative complications and mortality." (PMID 40134599, 2025). "The modified Glasgow Prognostic Score based on C-reactive protein and albumin has been proved to be associated with the risk of recurrence of bladder cancer." (PMID 39039528, 2024). "Previous studies have demonstrated that NLR, PLR, and fibrinogen are available biomarkers to predict LN metastasis, and other hematological indicators, like MLR and ALB, have been shown to be associated with pathologic stage or LN status of bladder carcinoma." (PMID 33123462, 2020). "Another study found that 197 of 1471 (13.4%) bladder cancer patients had a low serum albumin level, and low albumin level was independently associated with reduced recurrence-free survival (HR 1.68, P = 0.006) and overall survival (HR 1.93, P < 0.001)." (PMID 29335609, 2018). "A previous study observed bladder cancer patients after radical cystectomy and pelvic lymphadenectomy and showed that preoperative albumin, lymphocyte count, and platelet count were independently associated with a significantly increased risk of death from bladder cancer." (PMID 37456236, 2023). "On the other hand, we would like to highlight our findings regarding albumin in bladder cancer patients receiving ICI." (PMID 37036596, 2023). "Serum albumin levels are a predictive factor for this complication in the subgroup of patients with bladder cancer." (PMID 37036596, 2023). "The aim of our study was to investigate the preoperative fibrinogen-to-albumin ratio (FAR) as a preoperative predictor of malignancy as well as advanced grade in patients with bladder cancer." (PMID 36295649, 2022). "In conclusion, we consider that the preoperative serum albumin level can be a good prognostic factor for patients with bladder cancer because it plays an important role in evaluating the nutritional status and the systemic inflammatory response." (PMID 34232194, 2021). "Our study determined that a poor preoperative albumin level can predict poor OS in bladder cancer patients undergoing TURBT." (PMID 34232194, 2021). "Future prospective multicenter studies with a larger sample size are needed to verify the prognostic value of the preoperative albumin level for patients with bladder cancer treated with surgery." (PMID 34232194, 2021). "A previous study evaluating the effect of the CRP/albumin ratio on overall survival after radical cystectomy in bladder cancer patients found that a high CRP/albumin ratio was the most effective prognostic indicator." (PMID 33193910, 2020). "We aim to evaluate the prognostic value of HALP (hemoglobin, albumin, lymphocyte and platelet) and explore novel prognostic indexes for patients with bladder cancer after radical cystectomy." (PMID 29335609, 2018). "This experiment demonstrates the successful establishment of a BALB/c-nu mouse model of invasive bladder carcinoma, and shows that albumin-bound As2O3 is a promising drug for the treatment of bladder cancer." (PMID 25915411, 2015). "The infusion of albumin-bound As2O3 through the internal iliac artery is a promising method of bladder cancer therapy." (PMID 25915411, 2015). "In this experiment, the BALB/c-nu mouse model for invasive bladder carcinoma implanted with human bladder cancer cells was treated with infusion of albumin-bound As2O3 through the internal iliac artery." (PMID 25915411, 2015). "Nanoparticle albumin-bound (nab) paclitaxel has been shown to be effective in the treatment of metastatic breast, pancreatic, and bladder cancer." (PMID 25202467, 2014). "Nanoparticle albumin-bound-paclitaxel has been shown to be effective in the treatment of a number of malignancies including metastatic breast, pancreatic, and bladder cancer." (PMID 25202467, 2014).
bladder cancer (continued). "Similarly, in bladder cancer patients, an elevated preoperative fibrinogen-to-albumin ratio (FAR) has been identified as a potential predictor of malignancy and advanced grade." (PMID 39359427, 2024). "Serum albumin levels are a predictive factor in individuals with bladder cancer." (PMID 37036596, 2023). "Recent findings suggest that the control of the nutritional status score and the preoperative albumin to fibrinogen ratio could be prognostic values in patients with bladder cancer treated with radical cystectomy." (PMID 36829836, 2023). "In the present study, we evaluated the prognostic value of a recently reported index, HALP, which combined hemoglobin and albumin levels and lymphocyte and platelet count, and found it as a good prognostic index for overall survival of patients with bladder cancer after radical cystectomy." (PMID 29335609, 2018). "This work purposed to evaluate the prognostic prediction of the total psoas index (TPI), albumin–globulin score (AGS), and the combination of TPI and AGS (CTA) in bladder cancer (BCa) patients after radical cystectomy." (PMID 34616677, 2021). "The Gustave Roussy Immune Score (GRIm-score), which combines albumin, lactate dehydrogenase (LDH), and neutrophil-to-lymphocyte ratio (NLR), is a prognostic factor for solid tumors; however, its role in bladder cancer remains unclear." (PMID 41750722, 2026). "Additionally, SPP1 can also recognize albumin (ALB), integrin-A (ITGAV) and integrin-B (ITGB1) proteins whose expression was found to be highly increased at an early stage of bladder cancer development, using the TCGA-BLCA search engine." (PMID 38067407, 2023). "The surface coated with bovine serum albumin (BSA) was used to assess the level of non-specific adhesion for bladder cancer cells due to the weak interaction of cells with BSA." (PMID 37175920, 2023). "Herein, we applied clinically approved human serum albumin as the nanoreactor to encapsulate photosensitizers Chlorin e6 (Ce6) for enhancing their tumor accumulation and subsequently potent PDT effect against bladder cancer models." (PMID 36815900, 2023). "Many preoperative blood-based markers, such as albumin(ALB), C-reactive protein, neutrophil lymphocyte ratio, platelet lymphocyte ratio, and lymphocyte monocyte ratio, have been shown to be prognostic factors in bladder cancer." (PMID 33959511, 2021). "Herein, we employed clinically approved HSA as the carrier to encapsulate photosensitizer Chlorin e6 (Ce6) via well-defined precipitation inside albumin nanocage for targeted delivery of Ce6 and potent PDT effect against murine bladder cancer and restricted human bladder tumor tissue." (PMID 36815900, 2023). "Non-standard Abbreviations: BCa, bladder cancer; ROC, receiver operating characteristic; MS, mass spectrometry; HSA, human serum albumin; CIS, carcinoma in situ." (PMID 25915536, 2015).
pulmonary disease (46 papers, 2015 to 2026). "For instance, a study using machine learning algorithms identified underlying lung disease, smoking history, serum albumin levels, and radiotherapy history as important factors influencing CIP risk." (PMID 40989697, 2025). "Building upon previous research, we incorporated additional features such as albumin, total bilirubin, neutrophils, activated partial thromboplastin time, and underlying diseases such as pulmonary diseases, renal function diseases and cancer." (PMID 38698064, 2024). "Underlying lung disease, plasma albumin, serum creatinine, number of failing organs, and IMV duration were independent prognostic factors of weaning in MODSE patients with invasive mechanical ventilation." (PMID 32257085, 2020). "This study suggests that cetuximab can induce ILD, and the onset time may be associated with factors such as serum albumin levels and underlying pulmonary diseases." (PMID 40777125, 2025). "Multivariate logistic regression analyses revealed that underlying lung disease, plasma albumin, serum creatinine level, number of failing organs, and IMV duration were related to prognosis of weaning, with odds ratios (ORs) of 1.447, 0.820, 1.603, 2.374, and 3.105, respectively." (PMID 32257085, 2020). "For instance, a cohort study involving more than 370,000 participants revealed a significant association between liver function markers, such as ALT, TBIL, ALB, TP, GGT, and ALP, and an elevated risk of lung disease." (PMID 38616272, 2024). "The albumin level (p = 0.001) and the presence of lung disease (p = 0.013) had a single‐variable impact on prognosis." (PMID 36999931, 2023). "From the original set of 33 clinical variables, six were selected as the most relevant, namely: history of lung disease, age, hemoglobin (Hb), albumin (ALB), globulin (GLB), and blood urea nitrogen (BUN)." (PMID 35455654, 2022). "Levels can be many-fold higher with extra-corporeal membrane oxygenation and hemolytic anemias, but do not usually achieve the concentrations that we observed in plasma of infants with lung disease (~50% of albumin or ~1000 mg/dl)." (PMID 33301538, 2020). "A cavitary or diffuse pulmonary disease, to be homeless,unemployed, uneducated, smoker or need care, low weight,hemoglobine, leucocyte, albumin levels, high Charlson comorbidityindex, neutrophils and especially those with malignancy andchronic pulmonary disease are related with in-hospitalmortality." (PMID 38676595, 2024). "Hemoglobin, albumin, and fibrinogen participate in intravascular oncotic pressure; thus, their degradation could promote edema, which is a finding in lung disease." (PMID 38279292, 2024). "The ability to use Cy7-albumin 3D OI/CT imaging as a preclinical translational surrogate for 68Ga-albumin offers an accessible high throughput means to rapidly screen potential therapeutics against lung diseases that clinically manifest with endothelial permeability." (PMID 34766000, 2020). "In addition, we found that serum albumin and LDH were significantly different among the three groups, suggesting the role of albumin and LDH in the occurrence and development of pulmonary disease, especially LUAD." (PMID 37128769, 2023). "Without PS matching, the two groups showed significant differences in age, BMI, sex, ASA PS, smoking history, operator, surgical strategy, DM, HTN, IHD, pulmonary disease, clopidogrel, HMG-CoA reductase, NSAIDs, selective COX-2 inhibitor, CRP, AST, albumin, and echocardiographic/PFT findings." (PMID 31159309, 2019). "Whether or not correction for dilution in BAL fluid by using albumin should be performed is under debate, mainly as the albumin levels may be influenced by different airway/lung diseases." (PMID 31558154, 2019).
glioblastoma (45 papers, 2010 to 2026). The most malignant astrocytic tumor (WHO grade IV). "A study involving 214 glioblastoma patients demonstrated that albumin levels < 3 g/dL were associated with worse OS compared to levels ≥3 g/dL." (PMID 40283046, 2025). "Hypoxia and necrotic tumor cell-induced mediators are thought to be the reason for systemic inflammation, causing elevated CRP and reduced albumin levels in any cancer type, including Glioblastoma Multiforme." (PMID 40641926, 2025). "Our study is the first to address this gap by demonstrating that an albumin/D-dimer ratio < 6.5 is significantly associated with poorer OS in glioblastoma patients." (PMID 40283046, 2025). "Serum albumin level is associated with prognosis in glioblastoma patients, although the underlying mechanism is complex because of the role of serum albumin as a nutritional indicator and its involvement in inflammatory responses." (PMID 25880463, 2015). "Moreover, low serum albumin levels are associated with significantly short survival in glioblastoma patients." (PMID 28548947, 2017). "We showed that serum albumin level is associated with prognosis in glioblastoma patients." (PMID 25880463, 2015). "Similarly, serum albumin, a well-established marker of nutritional status and systemic inflammation, has been independently associated with survival across multiple malignancies, including glioblastoma." (PMID 40283046, 2025). "This study advances beyond current albumin-based glioblastoma nanocarriers by combining ATRA with curcumin in a single platform that ensures synchronized delivery and optimal drug ratios." (PMID 41598285, 2026). "This study aims to comprehensively evaluate the prognostic significance of coagulation biomarkers, including the novel albumin/D-dimer ratio, in adult glioblastoma patients." (PMID 40283046, 2025). "The WBC count, CRP/albumin ratio, and Ki-67 parameters can be used to predict 1-year overall survival in patients with glioblastoma multiforme." (PMID 40641926, 2025). "Despite these findings, no prior studies have investigated the prognostic relevance of albumin/D-dimer ratio in glioblastoma, highlighting a critical gap in the literature." (PMID 40283046, 2025). "This study underscores the important prognostic role of biomarkers, specifically D-dimer, PT, and albumin levels, in adult glioblastoma." (PMID 40283046, 2025). "This study aims to comprehensively investigate the prognostic significance of coagulation biomarkers and novel indices, such as the albumin/D-dimer ratio, in adult glioblastoma patients." (PMID 40283046, 2025). "Beyond the individual prognostic significance of albumin and D-dimer, our study also explored the prognostic value of the albumin/D-dimer ratio in glioblastoma." (PMID 40283046, 2025). "The unique properties of albumin as a carrier in nano drug delivery systems have been utilized for tumor-targeted delivery to glioblastoma cells, enhancing drug efficacy." (PMID 39272576, 2024). "In phase I of a phase I/II trial (NCT04528680), seventeen patients with recurrent glioblastoma were treated with albumin-bound paclitaxel and microbubbles in conjunction with low-intensity pulsed ultrasound (LIPU-MB)." (PMID 39451851, 2024). "The novelty of this review article consists of a critical analysis of the progress made by researchers until now in developing albumin-based nanoparticles that can improve the treatment of brain cancer, especially glioblastoma multiform." (PMID 37836018, 2023). "Currently, clinicaltrials.gov only lists two clinical trials related to using albumin nanoparticles in treating glioblastoma." (PMID 37836018, 2023). "Researchers have also tested albumin nanoparticles loaded with sirolimus, an mTOR inhibitor, against glioblastoma." (PMID 37836018, 2023). "Comparative studies have indeed reported differences in glioblastoma accumulation for small Gd complexes and radiolabeled albumin measured via PET." (PMID 37509598, 2023).
glioblastoma (continued). "For example, Altunbek and coworkers reported cytotoxicity and cycle perturbations in U373 human glioblastoma cells induced by pristine and ZnO-NP-bound albumin, fibrinogen and apo-transferrin (to the most abundant blood proteins)." (PMID 33669859, 2021). "IL-6 is implicated in the regulation of VEGF secretion from glioblastoma cells, and VEGF can induce vascular permeability, which contributes to decreasing serum albumin levels." (PMID 28548947, 2017). "Serum albumin levels were significantly correlated with overall survival in glioblastoma patients (multivariate HR = 0.966; 95% CI, 0.938-0.995; P = 0.023)." (PMID 25880463, 2015). "Serum albumin level is a reliable and convenient marker of the nutritional status of patients, and has been identified as a prognostic marker in glioblastoma." (PMID 25880463, 2015). "All 214 glioblastoma cases were used to construct a ROC curve to assess the prognostic performance of preoperative serum albumin level for glioblastoma patients." (PMID 25880463, 2015). "Next, we examined the survival function of preoperative serum albumin levels in glioblastoma patients." (PMID 25880463, 2015). "In the present study, we showed that serum albumin level was positively correlated with survival in glioblastoma patients." (PMID 25880463, 2015). "In the present study, we retrospectively analyzed 214 patients with glioblastoma treated in our neurosurgical center to examine the prognostic value of preoperative serum albumin levels." (PMID 25880463, 2015). "In this study, we found that preoperatively, serum albumin levels significantly correlated with other nutritional indicators, including serum prealbumin, total protein levels and total lymphocyte counts in glioblastoma patients." (PMID 25880463, 2015). "Kaplan–Meier analysis and Cox proportional hazards models were used to examine the survival function of preoperative serum albumin levels in these glioblastoma patients." (PMID 25880463, 2015). "Albumin levels in CSF have been noted to be elevated in patients with glioblastoma and has been attributed to either disturbance of the blood brain barrier or release from tumor." (PMID 23185417, 2012). "It was concluded that presurgical serum albumin levels can be used to evaluate the success of randomization of clinical trials for glioblastoma multiforme therapies." (PMID 21176210, 2010). "Moreover, composite indices, such as the albumin/D-dimer ratio, have demonstrated prognostic significance in other malignancies; however, their relevance in glioblastoma remains inadequately studied and warrants further investigation." (PMID 40283046, 2025). "Given the well-established interplay between coagulation, inflammation, and tumor progression, albumin/D-dimer ratio may serve as a novel and clinically relevant prognostic biomarker in glioblastoma." (PMID 40283046, 2025). "Importantly, this study represents a comprehensive evaluation of coagulation biomarkers in glioblastoma and introduces the albumin/D-dimer ratio as a novel composite biomarker for this patient population." (PMID 40283046, 2025). "Similarly, our study found that albumin levels < 4.3 g/dL were linked to poorer PFS and OS in glioblastoma patients." (PMID 40283046, 2025). "Moreover, pre-treatment serum albumin levels have been identified as prognostic indicators in glioblastoma." (PMID 40283046, 2025). "Albumin nanoparticles have shown promise in targeted drug delivery for glioblastoma therapy." (PMID 39272576, 2024). "In contrast, pretreatment serum albumin levels are prognostic for patients with glioblastoma." (PMID 28548947, 2017). "However, because of the recent wide application of standard radio-chemotherapy for the treatment of glioblastoma patients, the prognostic effect of preoperative serum albumin levels needs to be re-evaluated and the related mechanism should be further explored." (PMID 25880463, 2015).